XPO6P1 (XPO6 pseudogene 1)
Synonyms: formerly RANBP20P
Gene: Processed pseudogene on chromosome 14 (20,720,742 to 20,723,127, reverse strand). Ensembl gene ENSG00000259144.
Diseases named in the same sentence as XPO6P1 in open-access papers:
XPO6P1 is named in the same sentence as 1 disease in open-access papers, as found by Europe PMC text mining. Sharing a sentence is not in itself a finding about the gene and the disease.
XPO6P1 shares sentences with these, for which no sentence is quoted: lymph node metastasis (1 paper).